ASIC5 (acid sensing ion channel subunit family member 5)
Description:
Forms bile acid-gated sodium channels and may play a role in bile acid-dependent absorption and secretion by epithelial cells of the bile ducts. Displays high selectivity for sodium ions but can also permit the permeation of other cations (Probable). The gating could be indirect and the consequence of alterations of the membrane environment of the channel by bile acids (By similarity). As a sodium channel of type II unipolar brush cells of the vestibulocerebellum, controlling the electrical activity of these cells, could play a role in motor coordination and balance (By similarity).
Synonyms: BASIC; HINaC; ACCN5; INAC
Tractability: Small molecule: it belongs to a druggable protein family. Antibody: UniProt places it where antibodies can reach, with high confidence; its Gene Ontology location is reachable by antibodies, with high confidence; UniProt predicts a signal peptide or a membrane-spanning region.
Gene: Protein-coding gene on chromosome 4 (155,829,729 to 155,866,277, reverse strand). Ensembl gene ENSG00000256394.
Subcellular location: Apical cell membrane; Cell membrane
Pathways (Reactome):
Transport of small molecules: Stimuli-sensing channels
Gene Ontology:
Molecular function: bile acid-gated sodium channel activity; ligand-gated sodium channel activity; proton channel activity; sodium channel activity
Biological process: neuronal action potential; sodium ion import across plasma membrane; sodium ion transmembrane transport; proton transmembrane transport; sodium ion transport
Cellular component: plasma membrane; apical plasma membrane; membrane
Genetic constraint (gnomAD): Loss-of-function variants: 34 observed, 35.21 expected, observed/expected ratio (o/e) 0.97, 90% interval 0.73 to 1.29. The upper end of that interval is the gene's LOEUF score, 1.29, which puts it in group 5 of 6, group 1 being the genes least tolerant of losing a copy. Missense variants: 499 observed, 502.64 expected, observed/expected ratio (o/e) 0.99, 90% interval 0.92 to 1.07. Synonymous variants: 187 observed, 172.26 expected, observed/expected ratio (o/e) 1.09, 90% interval 0.96 to 1.23.
Homologues: Orthologues: chimpanzee ASIC5 (99% identical), macaque ASIC5 (95% identical), dog ASIC5 (83% identical), rabbit ASIC5 (82% identical), pig ASIC5 (80% identical), mouse Asic5 (77% identical), rat Asic5 (77% identical), guinea pig ASIC5 (74% identical), Drosophila melanogaster ppk26 (21% identical), Drosophila melanogaster rpk (20% identical), Drosophila melanogaster ppk (19% identical), Caenorhabditis elegans del-10 (18% identical). Paralogues in human: SCNN1G (25% identical), ASIC3 (25% identical), ASIC1 (25% identical), SCNN1B (24% identical), SCNN1A (24% identical), ASIC4 (23% identical), ASIC2 (23% identical), SCNN1D (21% identical).
Diseases named in the same sentence as ASIC5 in open-access papers:
ASIC5 is named in the same sentence as 9 diseases in open-access papers, as found by Europe PMC text mining. Sharing a sentence is not in itself a finding about the gene and the disease. The quoted sentences say what the papers report.
Ataxia (2 papers, 2020). Ataxia refers to impaired coordination of voluntary muscle movement. "Here we assessed motor coordination and balance to investigate if deletion of acid-sensing ion channel 5 (Asic5), which is richly expressed in type II UBCs, is sufficient to cause ataxia." (PMID 32034189, 2020). "There likely is a cause and effect relation between these two observations such that type II UBCs serve a key role in the vestibulocerebellum, and their dysfunction here due to abnormal Asic5 activity causes a mild form of ataxia." (PMID 32034189, 2020). "We argue this because deletion of Asic5 causes discoordination, Asic5 is restrictively expressed in type II UBCs29, type II UBCs are chiefly expressed in the vestibulocerebellum, and because cerebellar dysfunction is widely recognized as being capable of causing ataxia." (PMID 32034189, 2020). "The possible cellular mechanism underpinning ataxia in this global Asic5 knockout model was elaborated using brain slice electrophysiology." (PMID 32034189, 2020). "The current studies were designed to test the importance of Asic5 to type II UBC function and to test whether targeted dysfunction of type II UBCs was capable of causing ataxia." (PMID 32034189, 2020). "Tests of motor coordination and balance combined with electrophysiological analysis of type II UBCs in an Asic5 knockout mouse demonstrated that targeted disruption of normal type II UBC function was capable of causing ataxia." (PMID 32034189, 2020). "In Asic5 mutant mice, dysfunction of unipolar brush cells results in cerebellar ataxia." (PMID 32731618, 2020).
Anxiety (1 paper, 2020). Intense feelings of nervousness, tension, or panic often arise in response to interpersonal stresses. "One possibility could be that deletion of Asic5 causes an anxiety-like phenotype, which may have affected performance on the rotarod and balance beam." (PMID 32034189, 2020). "Because the open-field test is commonly used to assay anxiety-like behaviors and also quantifies activity in unchallenged animals, we tested performance of weanling Asic5 KO and littermate controls on this apparatus." (PMID 32034189, 2020). "While we think unlikely to explain the discoordination documented above in the Asic5 KO mouse, it was important to test if these mice had any anxiety-like behavior." (PMID 32034189, 2020). "Contributions made by vestibulocerebellum dysfunction to the discoordination observed in the Asic5 KO mouse could possibly be interacting with or confounded by changes in muscle function and anxiety behaviors, amongst other variables and tissue functions not investigated here." (PMID 32034189, 2020).
breast carcinoma (1 paper, 2023). "Nonetheless, since the function of ASIC5 remains unknown, further studies are necessary to establish the specific characteristics in breast cancer." (PMID 37859946, 2023).
glioblastoma (1 paper, 2021). The most malignant astrocytic tumor (WHO grade IV). "A recent study on the prognosis markers of glioblastoma revealed the expression of ASIC5 as associated prognosis markers." (PMID 34395479, 2021).
melanoma (1 paper, 2021). A malignant, usually aggressive tumor composed of atypical, neoplastic melanocytes. "Low (in 50%) ASIC5 protein expression in melanoma were observed with <4% mutation rates." (PMID 34395479, 2021).
ASIC5 also shares sentences with these, for which no sentence is quoted: infection (3 papers); cerebellar ataxia (2); Chlamydia infection (2); edema (1).